CRP (C-reactive protein)
Diseases named in the same sentence as CRP in open-access papers (continued):
Sharing a sentence is not in itself a finding about the gene and the disease.
peritonitis (continued). "Multivariate cox survival analysis showed that higher CRP level was the predictor of shorter duration to first peritonitis episode (HR 1.025, 95% CI 1.011 to 1.040, P = 0.001) for overall population." (PMID 25961883, 2015). "The highly sensitive C-reactive protein (hs-CRP) remains significantly higher than baseline even by day 42 after an episode of peritonitis." (PMID 20454534, 2010). "Minor criteria include bloody dialysate and calcification of the peritoneum, PD duration of longer than 8 years, a persistently positive C-reactive protein level, recurrent peritonitis, and development of a high peritoneal membrane transport state by PET." (PMID 21476232, 2010). "Within two weeks, her C-reactive protein decreased from 197.21 to 47.07 mg/L, NE% dropped from 89.7% to 53.8%, and her abdominal pain was alleviated, suggesting that Up played a significant role in her peritonitis." (PMID 40941729, 2025). "The prominent findings were microcytic anaemia, raised CRP which may have resulted from active inflammation and perforation, and raised lactate due to developing acute peritonitis." (PMID 40124694, 2025). "In particular, our preliminary data show that there is a significant increase in eryptosis levels in PD patients with peritonitis and significant positive correlations between the percentage of eryptosis and all systemic inflammatory markers tested (C-reactive protein, IL-1β and IL-6)." (PMID 38673869, 2024). "Parameters such as CRP levels, sedimentation rates, and patient age could serve as valuable indicators in discerning between various types of peritonitis." (PMID 38567242, 2024). "Notably, our analysis included only peritonitis episodes accompanied with a plasma CRP of 100 mg/l or higher." (PMID 37314998, 2023). "In addition, acute infection complications with very high levels of CRP, such as peritonitis, or pulmonary infection, were also excluded while our research was focus on the low-grade inflammation." (PMID 37587401, 2023). "After adjusting for age, gender, Charlson comorbidity index, PD vintage, Alb, Hb, Hs-CRP, and neutrophil/lymphocyte ratio, AID (adjusted OR = 1.45, 95% CI: 1.06–2.00, p = 0.02) was independently positively associated with the occurrence of peritonitis." (PMID 35458175, 2022). "For severity, they were CRP, peritonitis, and body temperature." (PMID 33996697, 2021). "In addition, an AUC value of DNI at a cutoff level of 0.9% displayed better accuracy than that of aPTT or CRP in Group I. Patients with acute peritonitis require an examination of the DNI value as a prognostic factor." (PMID 30985959, 2019). "Laboratory values that might indicate peritonitis are a CRP > 75 and white blood cell count > 10.000/mm3, although sensitivity and specificity of these tests are relatively low." (PMID 29946347, 2018). "We can also speculate that those patients had clear signs of peritonitis as the mean CRP was 86 mg/l which was nearly three times more than the median for the group of patients with radiological imaging." (PMID 27190551, 2016). "Overall, PCT has a higher discriminative capability than CRP in diagnosing peritonitis." (PMID 25145785, 2014). "Furthermore, CRP is most helpful as a clinical parameter among various proinflammatory markers for monitoring microinflammation in patients with peritonitis." (PMID 24007461, 2013). "In the present study, the PD-related peritonitis-free period was lower in patients with progressive hs-CRP elevation than in the other patients, which is in agreement with the results of previous studies showing the association between all-cause mortality and changes in the CRP level." (PMID 24007461, 2013). "Progressive rather than persistently high levels of serum hs-CRP predicted peritonitis risk in CAPD patients." (PMID 24007461, 2013).
peritonitis (continued). "Because variations in serum albumin levels are small, measurement of changes in CRP levels may provide greater insight into the dynamics of nutritional status and clinically relevant insults such as peritonitis." (PMID 24007461, 2013). "Inflammatory cytokines, including C-Reactive Protein, have been observed to be significantly elevated in the initial 48 hours of peritonitis and may remain elevated for weeks after the peritonitis episode." (PMID 16600033, 2006). "Moreover, an association between elevated CRP levels and the risk of peritonitis has not been investigated critically in PD patients." (PMID 24007461, 2013). "Our results showed that persistent high levels of hs-CRP were not related to peritonitis risk." (PMID 24007461, 2013). "Red blood cells, pre-albumin, albumin, ultrasensitive C-reactive protein (CRP), white blood cells (WBC), lymphocytes, neutrophils, globulins, and the incidence of peritonitis were measured." (PMID 39612406, 2024). "We found similar values for serum C-reactive protein (CRP) (p=0.12) and for peritonitis rates (P=0.63) in both groups." (PMID 34290791, 2021). "Postoperatively, he developed fever and elevated C-reactive protein levels without clinical or radiological evidence of peritonitis or shock." (PMID 42027451, 2026). "Additionally, there was a significant positive correlation between CRP and LOS among patients with peritonitis and a drainage tube." (PMID 39726534, 2024). "SII and CRP/HDL-C are practical and affordable parameters that could serve as novel indicators for patients with repeated episodes of peritonitis." (PMID 38443857, 2024). "In this study, roxadustat significantly reduced hepcidin levels without increasing high-sensitivity C-reactive protein level and the incidence of peritonitis." (PMID 37936193, 2023). "Patients with endoscopy-associated peritonitis had higher white blood cell counts, higher serum C-reactive protein levels, and lower serum calcium level than patients without peritonitis." (PMID 23936514, 2013). "Firstly, they compared eryptosis levels and systemic inflammatory markers (such as CRP, IL-6, and IL-1β) in 31 PD patients with acute peritonitis and 34 PD patients with no history of systemic inflammation or peritonitis in the past three months, representing the control group." (PMID 40643488, 2025). "Furthermore, based on our results in PD patients with peritonitis compared with PD patients without peritonitis, we observed elevated values of systemic C-reactive protein and elevated values of peritoneal inflammatory markers." (PMID 38673869, 2024).
pulmonary TB (71 papers, 2009 to 2026). "In elderly pulmonary TB, higher CRP associated with delayed smear conversion, adding a clinically practical bridge between inflammatory tone and time to microbiologic response." (PMID 41462913, 2025). "A SIRI value higher than 2.095 is significantly associated with cavitary pulmonary tuberculosis, and the combination of CRP and PLR can significantly enhance the diagnostic sensitivity for cavitary pulmonary tuberculosis." (PMID 40046059, 2025). "Evidence of a positive association between CRP and ferritin levels in various inflammatory diseases is previously documented.This correlation has also been observed in pulmonary TB patients." (PMID 39623309, 2024). "CRP is associated with multiple indices of disease severity among pulmonary TB cases in our study, suggesting that CRP-based triage is more likely to detect people who are more likely to transmit Mtb. and experience poor outcomes." (PMID 36375640, 2023). "Two previous systematic reviews assessed the diagnostic accuracy of C-reactive protein for pulmonary TB, the most recent of which reported pooled sensitivity of 89% (95%CI 80–96%) and specificity 57% (36–65%) using a threshold of ≥10 mg/L." (PMID 36375640, 2023). "Among people with culture-confirmed pulmonary TB, there was strong evidence for an association between higher CRP and higher indices of disease severity (lower BMI, shorter time to culture positivity, lower hemoglobin, and higher TB Score II; all p < 0·001)." (PMID 36375640, 2023). "Univariate logistic regression analysis found that BMI, pulmonary tuberculosis, operation time, operation blood loss, preoperative lymphocytes, preoperative serum albumin, preoperative CRP, and preoperative ESR are risk factors." (PMID 35571899, 2022). "A recent meta-analysis of diagnostic accuracy studies found CRP to perform with an overall sensitivity and specificity of 89% and 57% respectively for pulmonary TB, showing significant variation by geography, HIV status and clinical setting." (PMID 34252128, 2021). "We did not analyze other non-specific biomarkers of inflammatory response associated with severe pulmonary TB, such as C-reactive protein, albumin and globulin." (PMID 34276654, 2021). "The objective of the study was to explore the association between the CRP +1444C/T polymorphism with the susceptibility to pulmonary tuberculosis (PTB) in a Chinese population." (PMID 33415152, 2020). "A low CRP level and poor performance status were associated with non-cavity and non-upper predominant lung distribution, respectively, in patients with pulmonary tuberculosis." (PMID 31344108, 2019). "In pulmonary tuberculosis, elevation of CRP is detected and a high CRP is clearly associated with more severe disease." (PMID 28835282, 2017). "The decreasing levels of RBCs, WBCs, and platelet count, and elevated erythrocyte sedimentation rate (ESR) and C-reactive protein (CRP) that indicate acute inflammation also acted as inflammatory diagnostic markers in pulmonary TB and correlated with disease severity and prognosis." (PMID 41041335, 2025). "Elevated CRP levels may indicate the pulmonary TB severity, as they are associated with prolonged sputum conversion time in severe cases." (PMID 39882120, 2024). "•CRP has good diagnostic accuracy for pulmonary TB among symptomatic adults." (PMID 36375640, 2023). "However, whereas both Fibrinogen and CRP had high diagnostic utility in the current study, Fibrinogen appeared to have lower diagnostic utility in pulmonary TB with one study reporting an AUC of 0.70 for Fibrinogen versus 0.86 for CRP." (PMID 34868023, 2021). "Elevated serum levels of sTREM-1 and CRP correlated with more advanced pulmonary involvement, higher bacteria burden in sputum, and were independent factors associated with on-treatment mortality in patients with pulmonary TB." (PMID 29844416, 2018).
pulmonary TB (continued). "In this study among HIV-positive and negative children presenting to public health facilities in Lusaka, Zambia, POC CRP demonstrated limited utility as a standalone screening tool for pulmonary TB." (PMID 39446791, 2024). "Heterogeneity was assessed for biomarkers that reported sensitivity and specificity in at least four studies for adult pulmonary TB (CRP, HO-1, IFN-γ, IL-6, IP-10, MIG, TNF, and VEGF)." (PMID 39445833, 2024). "A study from India evaluating acute phase proteins in the serum of pulmonary TB and TB lymphadenitis patients found elevated serum CRP levels (median: 1692 pg/ml or 16.92 mg/L) in 44 TB lymphadenitis patients as compared to the healthy controls." (PMID 39623309, 2024). "Comparing CAD4TB, Xpert HR, and CRP, we found that CAD4TBwas the most accurate TB triage test for pulmonary TB and the only test that met WHO TPP specificity targets (≥70% at ≥90% sensitivity) in a multi-country cohort of people with presumptive TB." (PMID 38947093, 2024). "Pulmonary TB is characterized by excessive inflammation, and we identified numerous inflammation-related proteins such as CRP, S100A8, and S100A9." (PMID 38512356, 2024). "Another study also reported a significant correlation between ferritin and CRP with disease severity in pulmonary TB." (PMID 39623309, 2024). "In our study population, with very high prevalence of pulmonary TB (27%), a CRP-based triage strategy would lead to 41% fewer confirmatory tests than a test all approach but would miss 7% of TB cases." (PMID 36375640, 2023). "In this population, assuming that the whole study population would usually be systematically tested for pulmonary TB, use of CRP-based triage (≥10 mg/L) would have avoided 382/932 (41%) of confirmatory tests but would miss 18/255 (7%) of pulmonary TB cases." (PMID 36375640, 2023). "At the observed TB prevalence (27%), CRP-based triage demonstrated higher net benefit than a strategy of confirmatory testing for all when the NWT per true positive pulmonary TB case detected was up to 20, reflecting a threshold probability of at least 5%." (PMID 36375640, 2023). "The numbers needed to test with culture to detect a true pulmonary TB case were 2·3 and 20 among CRP-positive and CRP-negative participants respectively." (PMID 36375640, 2023). "The levels of serum C-reactive protein (CRP) are known to correlate highly with pulmonary TB in macaques." (PMID 35631065, 2022). "Previous studies have only looked at CRP as a screening tool for the detection of pulmonary tuberculosis in people living with HIV." (PMID 35806852, 2022). "Ours is the first to have studied the utility of CRP as a screening tool for both pulmonary as well as extra pulmonary tuberculosis." (PMID 35806852, 2022). "When considering combinations of biomarkers from previous studies, the existing pulmonary TB biosignature of CRP and CCL1 performed well in the current study, achieving an AUC of 0.95 compared to 0.90 in the original test set of suspected pulmonary TB." (PMID 34868023, 2021). "For the existing two-biomarker adult pulmonary TB-derived signature, CRP contributed significantly to the model (p < 0.001) but CCL1 did not (p = 0.91)." (PMID 34868023, 2021). "CRP levels have been shown to depend on the virulence of the Mtb strain and the location of the infection, for example, pulmonary TB and miliary TB show higher levels of CRP." (PMID 34691031, 2021). "We found that pulmonary TB patients generally exhibited a distinct profile of gamma-glutamyl transferase (gamma-GT), and, expectedly, of CRP, erythrocyte sedimentation rate (ESR), uric acid and ferritin." (PMID 30718725, 2019). "Conversely, our findings differed from a previous South African study that reported good discrimintaion of CRP (ROC AUC of 0.87) when comparing participants with pneumococcal community-acquired pneumonia and pulmonary tuberculosis." (PMID 30107791, 2018).
pulmonary TB (continued). "In the present study, we tested if circulating levels of C-reactive protein (CRP) and ferritin reflect mycobacterial loads and inflammation in pulmonary TB (PTB) patients undergoing anti-tuberculous therapy (ATT)." (PMID 28384354, 2017). "The presence of CMV DNA did not associate with HIV RNA levels (Mann–Whitney, p = 0.53), CD4 T-cell counts (p = 0.31) or CRP levels (p = 0.81), but was more common in patients with pulmonary tuberculosis (χ2, p = 0.04)." (PMID 28859681, 2017). "Regarding the implications for clinical practice, TRIAD-TB offers a pragmatic, bedside-ready way to identify pulmonary TB inpatients at the highest short-term risk using data every ward already collects (vitals, CBC-derived SII, CRP, BMI, albumin) and their 72 h trajectories." (PMID 41462913, 2025). "However, a study from Pakistan on children demonstrated significantly increased ferritin and CRP levels in confirmed pulmonary TB as compared to clinically diagnosed (probable and possible) pulmonary TB cases." (PMID 39623309, 2024). "In decision curve analysis, CRP-based triage offered greater clinical utility than confirmatory testing for all up to a number willing to test threshold of 20 confirmatory tests per true positive pulmonary TB case diagnosed (threshold probability 5%)." (PMID 36375640, 2023). "Our study is the first, to our knowledge, to report the diagnostic accuracy of CRP for pulmonary TB in a large, consecutive cohort of outpatients presenting with symptoms compatible with TB and mixed HIV status; and is the first to benchmark CRP-based triage against an Ultra-reference standard." (PMID 36375640, 2023). "Future studies should evaluate performance of CRP for extra-pulmonary TB." (PMID 36375640, 2023). "The overall AUROC of CRP for culture-positive pulmonary TB was 0.80 (95%CI 0.77–0.83)." (PMID 36375640, 2023). "In this regard, a recent meta-analysis has shown that in TB patients infected with HIV, CRP has high sensitivity and moderate specificity for active pulmonary TB, suggesting that CRP could be used for screening of active TB." (PMID 36189292, 2022). "This study demonstrated that a low CRP level and poor PS were associated with non-cavity and non-upper predominant lung distribution, respectively, in patients with pulmonary TB." (PMID 31344108, 2019). "In conclusion, a low CRP level and poor PS were associated with non-cavity and non-upper predominant lung distribution, respectively, in patients with pulmonary TB." (PMID 31344108, 2019). "Thus, the aim of this study was to assess the relationship between immune activation markers: C-reactive protein (CRP), Beta2 microglobulin (B2M) and Neopterin, disease severity prior to treatment and response to therapy in adult pulmonary TB patients." (PMID 26951717, 2016). "Our data indicate that CRP may be a useful marker for pulmonary TB treatment monitoring and future studies should analyse earlier time-points post-treatment initiation." (PMID 26951717, 2016). "Likewise, increased mean platelet volume parallels radiological extent of disease in active TB patients as reduced haemoglobin correlates with C-reactive protein and erythrocyte sedimentation rate in newly diagnosed and active pulmonary TB patients." (PMID 26880909, 2016). "We have previously shown in a diagnostic accuracy study for pulmonary TB among PLWH that these RNA biomarkers show greater correlation to each other than to CRP23, suggesting that TB associated blood transcriptional changes are regulated differently to that of CRP levels." (PMID 38946942, 2024). "However, the association between the CRP +1444C/T (rs1130864) polymorphism and the susceptibility to pulmonary TB (PTB) is not yet studied." (PMID 33415152, 2020).